FAT1 (FAT atypical cadherin 1)
Diseases named in the same sentence as FAT1 in open-access papers (continued):
Sharing a sentence is not in itself a finding about the gene and the disease.
head and neck cancer (15 papers, 2016 to 2025). A primary or metastatic malignant neoplasm affecting the head and neck. "Recent advances in the role of the Hippo pathway in head and neck cancer have provided evidence that genetic alterations of PIK3CA or functional loss of FAT1 (FAT atypical cadherin 1) can result in YAP activation." (PMID 38893204, 2024). "The second highest cdNS values (cdNS = 7.312) was noted for NHLRC1 mutation contexts for FAT1 truncating mutations in head and neck cancers." (PMID 39160568, 2024). "In head and neck cancer, FAT1 mutations have been described as marker for disease progression and adverse overall survival (OS) despite enrichment in cisplatin responders." (PMID 36653435, 2023). "The most significant gene, FAT1, was found in head and neck cancer in TCGA and included 21 APOBEC-associated SGMs (1 SBS13 SGM expected, P = 8.3 × 10−18)." (PMID 37922356, 2023). "For the example of FAT1, our study finds relevant interacting mutations in breast, colorectal, endometrial, kidney, lung, liver, stomach and head and neck cancer, with mutation rates between 2 and 24%." (PMID 30341300, 2018). "Therefore, FAT1 mutated HPV-negative head and neck cancer is considered a unique subtype with respect for genetic landscape and prognosis." (PMID 36653435, 2023). "Young-onset head and neck cancer patients with FAT1 germline variants had a shorter overall survival; therefore, restoration of the functional NOTCH1 or FAT1 expression in nonsense mutation NOTCH1 or FAT1 in HSNCC is a key issue in anticancer therapy." (PMID 36428516, 2022). "The functional loss of mutated FAT1 has also been reported to be associated with YAP1 activation in head and neck cancer, however, no enrichment of FAT1 mutation was seen among the YAP1-dependent nor WWTR1-dependent models in this study." (PMID 32990596, 2020). "However, other mutations, such as Notch1, CDKN2A, FAT1, PTEN HRAS, and PI3KCA, frequently occurring in head and neck cancer, may influence metastatic events." (PMID 37894373, 2023).
oral cancer (15 papers, 2012 to 2025). "While FAT1 upregulation has been shown to promote cancers of liver, brain, breast, colon, and pancreas; mutations in FAT1 have been found to promote skin, lung, head and neck and oral cancers." (PMID 33878524, 2021). "Homozygous loss of FAT1 has been reported in a study of oral cancer." (PMID 26247464, 2015). "FAT1 encodes for a cadherin protein implicated in the adhesion and migration of oral cancer cells." (PMID 26247464, 2015). "FAT1 regulates extracellular matrix architecture and cell adhesion while acting as a tumor suppressor in oral cancers in a context-dependent manner." (PMID 34070941, 2021). "Homozygous deletions of the FAT1 gene, a putative upstream negative regulator of Hippo signaling, were discovered in 23% of oral cancer cell lines and 80% of primary oral cancers." (PMID 25097728, 2014). "FAT1 is repressed in oral cancer owing to homozygous deletion or epigenetic silencing and is preferentially downregulated in invasive breast cancer." (PMID 23076869, 2012). "The human FAT1 gene is homozygously deleted in 23% of oral cancer cell lines and in 80% of primary oral cancer cases and FAT1 mRNA expression is repressed in oral cancer cell lines due to homozygous deletion and/or promoter CpG hypermethylation." (PMID 23076869, 2012). "FAT1 is downregulated in oral cancer and invasive breast cancer due to deletion and/or epigenetic silencing, whereas FAT1 is upregulated in leukemia and prognosis of preB-ALL with FAT1 upregulation is poor." (PMID 23076869, 2012). "Previous genomic data have begun to reveal subgroups of oral cancers with distinct molecular profiles and unique molecular drivers, including a subgroup of CASP8 (OMIM 601763) patients with or without FAT1 (OMIM 600976) mutations." (PMID 40974176, 2025).
esophageal squamous cell carcinoma (14 papers, 2017 to 2026). Esophageal squamous cell carcinoma (ESCC) is a type of esophageal carcinoma (EC) that can affect any part of the esophagus, but is usually located in the upper or middle third. "Esophageal squamous cell carcinoma cases in the NC group were highly significantly associated with the presence of significantly mutated genes (SMGs) including KMT2D, FAT1, and NOTCH1 mutations." (PMID 36741715, 2022). "Integrated genomic analysis has identified FAT1 as an additional driver gene, which has been detected mutant in several large-scale exome sequencing projects, frequently in esophageal squamous cell carcinoma (ESCC) and OSCC." (PMID 35646625, 2022). "In esophageal SCC, FAT1 has been reported to inhibit tumor growth and epithelial–mesenchymal transition, which is an important step during metastasis." (PMID 33527763, 2021). "The present study investigated the significance of circular FAT1 (circFAT1) as a novel biomarker in esophageal squamous cell carcinoma (ESCC)." (PMID 34185205, 2021). "It was found that FAT1 could suppress cell migration and invasion by affecting the cellular mechanical properties in esophageal squamous cell carcinoma." (PMID 34712552, 2021). "Many studies have shown the tumor-suppressing role of FAT1 in esophageal cancer cell lines and esophageal squamous cell carcinoma (ESCC) tissues." (PMID 39409043, 2024). "In other SCCs, such as esophageal squamous cell carcinoma (ESCC) and hepatocellular carcinoma (HCC), FAT1 was found to be a negative regulator of the epithelial–mesenchymal transition (EMT), with the loss of function of FAT1 promoting EMT, cell growth, migration, and invasion." (PMID 39199674, 2024).
colitis (13 papers, 2014 to 2025). Inflammation of the colon. "In order to document how fat-1 TG mice inhibited the colitis-associated cancer induced by combination of AOM and DSS, we hypothesized that the anti-tumorigenic effect of fat-1 TG mice might be due to subsequently decreased nuclear translocation of β-catenin." (PMID 27566583, 2016). "Hence, we compared the AOM-initiated, DSS-promoted colitis-associated carcinogenesis in Wild-type (WT) and fat-1 TG mice to obta in vivo confirmation that ω-3 PUFAs can prevent CAC." (PMID 27566583, 2016). "Moreover, transgenic mice expressing the fat-1 gene encoding n-3 FAs desaturase that produces n-3 FAs from n-6 acids were used to examine the impact of enhanced n-3 PUFA tissue status on the development of colitis." (PMID 32370215, 2020). "This was supported using the Fat-1 mouse model, which constitutively produces n-3 PUFAs and in which chronic colitis was induced by dextran–sodium–sulfate (DSS) during 3 cycles of 5 days." (PMID 40219010, 2025). "They showed that fat-1 transgenic mice subjected to the DSS protocol of chemically induced experimental colitis, had significantly reduced signs of colon inflammation, in terms of both clinical manifestation and pathology, than wild-type littermates." (PMID 29109724, 2017). "Enriched n-3 PUFA tissue levels in Fat-1 mice corresponded to reduced colitis severity and the decreased percentages of proinflammatory Th17 and Th1 cells within the colon lamina propria, the MLN, and the spleen." (PMID 25136149, 2014). "In transgenic fat1 mice expressing an n3-PUFA generating desaturase, a protective effect was observed after DSS-induced colitis, which was attributed to the high concentrations of 12-HEPE, the major 15-LOX metabolite of EPA in mice." (PMID 38675565, 2024). "Transgenic fat1 mice, which are rich in endogenous n-3 PUFAs, are protected in the DSS-induced colitis model but additional systemic inactivation of the Alox15 gene counteracted this protective effect." (PMID 37498393, 2023). "The Fat-1 mouse, a genetic model that synthesizes long-chain n-3 PUFA de novo, was shown to be relatively resistant to colitis induction due to a reduced differentiation of Th17 cells and related cytokines." (PMID 24611066, 2014). "Moreover, the 15-LOX metabolite 15-HEPE was also reduced in ALOX15-silenced fat1 transgenic mice, and the wild-type mice were protected against the development of DSS-induced colitis after intraperitoneal injections with 15-HEPE." (PMID 38675565, 2024). "Moreover, when Fat-1 mice were also treated with the carcinogen azoxymethane prior to DSS, an enhanced ability to resolve colitis and a reduced number of colonic adenocarcinomas per mouse were observed." (PMID 26301240, 2015).
leukemia (13 papers, 2010 to 2025). A malignant (clonal) hematologic disorder, involving hematopoietic stem cells and characterized by the presence of primitive or atypical myeloid or lymphoid cells in the bone marrow and the blood. "The leukemia specific expression of FAT1 in T-ALL leukemogenesis highlights its potential impact for translation into diagnostics and therapeutics." (PMID 36653435, 2023). "Next-generation sequencing (NGS) targeting 172 leukemia- and lymphoma-related genes identified ANKRD26-p.Asn267Ser, PTPN11-p.Glu76Lys, CIITA-p.His1119Asn and FAT1-p.Phe765Tyr mutations." (PMID 35912172, 2022). "FAT1 expression is up-regulated in patients with leukemia and pre B-acute lymphoblastic leukemia, suggesting that FAT1 function is distinct depending on the cell context." (PMID 29228735, 2017). "On the other hand, FAT1 is upregulated in leukemia and prognosis of preB-ALL patients with FAT1 upregulation is poor." (PMID 23076869, 2012). "These involve genes which are known to be leukemia drivers (such as FAT1, NOTCH1, PHF6, FLT3), and can activate signaling pathways that push the cells to multiply faster, as well as genes involved in ribosome biogenesis or translational control (such as WDR36 and LTV1)." (PMID 36482893, 2022). "The human FAT1 gene, initially referred to as FAT, was cloned in 1995 from a T-leukemia cell line." (PMID 35647082, 2022).
Obesity (12 papers, 2013 to 2025). Accumulation of substantial excess body fat. "For example, the FAT1 gene is associated with lipid metabolism and any disturbance in this gene contributes to metabolic disorders and obesity." (PMID 40024983, 2025). "We are not the first ones to report sex-specific differences in Fat-1 mice; a recent study investigating the role of elevated tissue levels of ω-3 fatty acids in obesity-associated post-traumatic osteoarthritis also reported sex-specific differences in Fat-1 transgenic mice." (PMID 35095496, 2021). "In this study, we utilized the Fat-1 transgenic mouse to test whether increasing the maternal n-3/n-6 tissue fatty acid ratio could reduce the consequences of maternal obesity-associated inflammation and thereby mitigate downstream developmental programming." (PMID 23825686, 2013). "Although several studies have used fat-1 transgenic mouse model to investigate the effects of n-3 PUFAs on obesity, diabetes, and NAFLD, the present study is the first using the model to specifically investigate how n-3 PUFAs regulate brown fat function." (PMID 36233205, 2022). "The single nucleotide variants (SNV) described to be associated with obesity are rs9923451 (16: 1677509940) and rs925642 (4: 187915860) for WWOX and FAT1, respectively." (PMID 35170849, 2022). "For example, the study of Fat-1 mouse, which is able to synthesize ω3 PUFAs itself, displays a lowered inflammatory environment induced by obesity, correlatively to 17-HDoHE synthesis." (PMID 30791540, 2019). "WT and Fat-1 female littermates were placed HFD for 8 weeks prior to mating to establish an obesity phenotype." (PMID 23825686, 2013). "This suggested that omega-3 fatty acids present in PO could attenuate obesity which was in agreement with some previous reports on PO and fat-1 transgenic mice." (PMID 35885367, 2022). "A study using Fat-1 transgenic mice (capable of endogenously converting n-6 PUFA to n-3 PUFA), demonstrated the potential to reduce inflammation associated with diet-induced obesity and improve metabolic outcomes in offspring." (PMID 29695082, 2018).
gastric cancer (11 papers, 2016 to 2025). A primary or metastatic malignant neoplasm involving the stomach. "FLNC suppresses gastric cancer progression by stabilizing TRIM54 and is linked to cytoskeletal remodeling, a process modulated by FAT1 in EMT." (PMID 40672387, 2025). "FAT1 expression is elevated in human samples of gastric cancer as well as in a model of this disease, and the knockdown of FAT1 in gastric cancer cell lines impairs cell migration and invasion." (PMID 37371091, 2023). "Of note, recent reports have underscored the pivotal roles of these genes in tumorigenesis, invasion, and prognosis (e.g., COL12A1 in gastric cancer, FAT1, and FBN1/2 in HCC)." (PMID 36900398, 2023). "TFAP2C collaborating with LINC00857, boosts FAT atypical cadherin 1 (FAT1) expression (highly expressed in gastric cancer)to drive tumorigenesis and EMT." (PMID 37291585, 2023). "GSE15459, SGE23377 and GSE14210 data set was from gastric cancer patients after surgery and found that patients with tumors highly expressing FAT1 had a worse prognosis." (PMID 29228735, 2017). "They demonstrated that verteporfin could suppress FAT1 expression, leading to decreased migration and invasion of gastric cancer cells." (PMID 35965328, 2022). "The positive correlation of FAT1 and NFкB (RelA) in other tumors like pancreatic, hepatocellular, lung and stomach cancers suggests that the same mechanism may be operative in these tumors also." (PMID 31992226, 2020). "Moreover, aside its ability to induce metastasis and progression of hepatocellular carcinoma upon interaction with POU2F1/OCT1, FAT1 expression has been shown to be up-regulated in metastatic gastric cancer, and patients with FAT1high gastric cancer had worse prognosis." (PMID 31783581, 2019). "For example, there is direct binding between Y-box binding protein-1 (YBX1) and circFAT1 (e2) from exon 2 of FAT atypical cadherin 1 (FAT1), which can inhibit the progression of gastric cancer." (PMID 34277605, 2021).
hepatocellular carcinoma (11 papers, 2019 to 2025). A malignant tumor that arises from hepatocytes. "On the contrary, when cells were grown in a simulated blood environment, FAT1 knockdown in hepatocellular carcinoma cell lines enhanced cell migration and invasion, and the loss of FAT1 in oral squamous cell carcinoma cells increased cell migration in a different study." (PMID 37371091, 2023). "FAT1 expression is elevated in both hepatocellular carcinoma and oral squamous cell carcinoma cell lines; notably, FAT1 knockdown impairs the migration or invasion of these cells." (PMID 37371091, 2023). "For example, POU2F1 promotes the growth and metastasis of hepatocellular carcinoma through the FAT1 signaling pathway." (PMID 37370118, 2023). "POU2F1 promotes growth and metastasis of hepatocellular carcinoma (HCC) through the FAT1 pathway." (PMID 34257651, 2021). "Conversely, aberrant expression of FAT1 has been implicated in the high invasiveness of GBM cells, cancerous cell proliferation, apoptosis evasion and disease progression in hepatocellular carcinoma (HCC), relapse and poor prognosis in patients with B-cell acute lymphoblastic leukemia." (PMID 31783581, 2019).